CCL3 (C-C motif chemokine ligand 3)
Diseases named in the same sentence as CCL3 in open-access papers (continued):
Sharing a sentence is not in itself a finding about the gene and the disease.
pulmonary embolism (1 paper, 2018). The obstruction of the pulmonary artery or one of its branches by an embolus, sometimes associated with infarction of the lung. "This could, at least partly, explain why RV dysfunction after pulmonary embolism was associated with increased expression of MCP-1 and C-C motif chemokine ligand 3 (CCL3 or MIP-1α), as well as RV infiltration with neutrophil and monocyte/macrophage." (PMID 30177883, 2018).
pulmonary sarcoidosis (1 paper, 2011). Sarcoidosis affecting the lung parenchyma. "In an effort to clarify discrepancies between these studies, we performed the largest observational study involving BALF CC chemokines (CCL2, CCL3, CCL4, and CCL5) during the pathogenesis of pulmonary sarcoidosis." (PMID 21463523, 2011). "BALF CCL3 and CCL4 levels from pulmonary sarcoidosis patients were not increased compared to controls." (PMID 21463523, 2011). "Furthermore, based on our results as well as those from other investigators we think that CCL3 and CCL4 do not have a substantial role in the pathogenesis of pulmonary sarcoidosis." (PMID 21463523, 2011).
pulpitis (1 paper, 2025). Inflammation of the dental pulp. "Multiple immunofluorescence staining reveals that typical TLS emerges in dental pulp with pulpitis, consistent with the high expression of CC chemokine ligand 3 (CCL3), which may be a key driver of TLS formation." (PMID 39465672, 2025).
respiratory allergies (1 paper, 2020). "The present study compared serum concentrations of CCL3 in patients with AR and healthy controls and correlated these concentrations with various aspects of respiratory allergies." (PMID 32461855, 2020). "The association between CCL3 concentration and NMH confirms that CCL3 plays a role in the pathogenesis of chronic inflammation, including respiratory allergies." (PMID 32461855, 2020). "Several studies in humans have investigated the role of CCL3 in respiratory allergies." (PMID 32461855, 2020).
ROSAH syndrome (1 paper, 2025). "ADP-heptose-dependent IL-8, CCL3 and TNF secretions were increased in the supernatant of monocytes from ROSAH syndrome patients in the presence of IFN-γ." (PMID 39868044, 2025).
scleroderma (1 paper, 2021). Scleroderma is a rare autoimmune connective tissue disorder characterized by abnormal hardening of the skin and, sometimes, other organs. "The early expression of CCL2, CCL3 and CCL5 is also observed in a mouse model of scleroderma, with a subsequent rapid reduction of CCL5 and maintained high expression of CCL2 and CCL3." (PMID 33313931, 2021).
sleep disorder (1 paper, 2023). A change from the patient's baseline sleeping pattern, in the hours slept and/or an alteration/dysfunction in the stages of sleep. "Sleep disorders, including RBD and ESS, exhibit significantly altered levels of IL-6, CRP, IL-1β, sTREM2, CCL3 and NO, suggesting these markers represent potential markers in PD patients." (PMID 36739284, 2023).
thyroid cancer (1 paper, 2021). "Most chemokines were downregulated in thyroid cancer, including CCL3, CCL4, CCL15, CCL21, and CXCL13." (PMID 33414407, 2021).
Tinnitus (1 paper, 2023). Tinnitus is an auditory perception that can be described as the experience of sound, in the ear or in the head, in the absence of external acoustic stimulation. "Proteins showing significance before correction for association with tinnitus were NT-3, uPA, and CX3CL1 when using the whole sample, and NT-3, CX3CL1, and CCL3 when using discordant twins." (PMID 38079022, 2023).
tongue cancer (1 paper, 2017). A malignant neoplasm affecting the tongue. "We first observed an increased mRNA expression of Ccl3 and Ccr5 in experimentally-induced tongue carcinomas." (PMID 28881626, 2017).
tongue tumours (1 paper, 2017). "CCL3-/- and CCR5-/- mice presented reduced incidence of tongue tumours compared to wild-type (WT) and CCR1-/- mice." (PMID 28881626, 2017).
toxoplasmosis (1 paper, 2024). A parasitic disease contracted by the ingestion or fetal transmission of toxoplasma gondii. "So, it is likely that the upregulated inflammatory genes, such as Ccl5, Ccl3, Ccl7, Ccr5, and Cxcr3, could be the key factors that cause mouse reproductive organ damage, and then contribute to the tragic pregnancy outcomes of toxoplasmosis." (PMID 39006750, 2024).
Trichiasis (1 paper, 2019). Inversion and rubbing of the eyelashes against the globe of the eye. "The upregulation of pro-inflammatory mediators and cell markers (CCL2, CCL3, CXCL5,IL1B, IL6, CHUK, FUT4 andPTPRC) is indicative of higher levels of inflammation and leukocyte infiltration in the conjunctival tissue of patients who developed ECA following trichiasis surgery." (PMID 37426632, 2019).
tubulointerstitial nephritis (1 paper, 2020). "In a model of tubulointerstitial nephritis, CCL3 and CCR5 knockout animals demonstrated better renal histology, less inflammatory infiltration, lower levels of serum creatinine, and reduced expression of KIM-1, TNF-α, and collagen in the renal tissue." (PMID 32961903, 2020).
Ureteral obstruction (1 paper, 2019). Obstruction of the flow of urine through the ureter. "Although some genes, such as Ccl3 and Cxcr4, changed persistently, the changes of many genes were temporarily observed after unilateral ureteral obstruction." (PMID 30949209, 2019). "Otherwise, many of these genes, such as Agt, Ccl12, Col3a1, Dcn, Itgb6, and Thbs2, were temporarily changed in these MSLCs expanded from the left kidney at only 7 days after ureteral obstruction, but the changes of Ccl3 and Cxcr4 were constantly observed during the 14 days of follow-up." (PMID 30949209, 2019).
viral meningitis (1 paper, 2019). Inflammation of the membranes surrounding the brain and spinal cord due to a viral infection. "The chemokines CCL3, CCL7, CCL8, and CXCL9 were all significantly elevated in patients with LNB and bacterial and viral meningitis." (PMID 31727097, 2019).
vitamin D (1 paper, 2014). "Upon A. fumigatus exposure, vitamin D deficiency led to enhanced and sustained expression of TNF-α, IL-1β, IL-6, CXCL1 and CCL3 both in vivo and in vitro." (PMID 24926881, 2014).
vitiligo (1 paper, 2023). Generalized well circumscribed patches of leukoderma that are generally distributed over symmetric body locations and is due to autoimmune destruction of melanocytes. "Nonetheless, a decreased production of CCL3 by vitiligo melanocytes has been reported." (PMID 36911664, 2023). "CCL3 was upregulated in CD8+ T cells of lesional and non-lesional vitiligo skin." (PMID 36911664, 2023).
infection (714 papers, 2004 to 2026). The state of being infected such as from the introduction of a foreign agent such as serum, vaccine, antigenic substance or organism. "CCL3, also referred to as Macrophage Inflammatory Protein-1α (MIP-1α), encodes a chemokine that directs the migration of immune cells, particularly leukocytes, to sites of inflammation or infection." (PMID 41208992, 2025). "Additional cytokine/chemokine transcripts induced by invasive infection were e.g., Ccl3, Ccl4, Ccl7, Cxcl10, and Csf2 (encoding GM-CSF)." (PMID 38291037, 2024). "At day 3 post-infection, young and aged neutrophils expressed similar levels of Il1b, but young neutrophils expressed higher levels of Il1a; the chemokines Ccl3, Cxcl3, and Cxcl1; and Cd274 (encodes PD-L1)." (PMID 37852965, 2023). "The chemokine receptors CCR2 (CCL2/MCP-1 receptor) and CCR5 (CCL3/MIP-1A receptor) in deficient mice exhibit defects in directing inflammatory cells to airways after infection." (PMID 36119044, 2022). "Peritoneal macrophages obtained of NI ccl3+/+ mice were susceptible to in vitro infection by trypomastigote forms of the Colombian strain, which triggered the production of NOx, TNF and IL-10." (PMID 32194558, 2020). "We induced CCC in C57BL/6 (ccl3+/+) and CCL3-deficient (ccl3−/−) mice by infection with the Colombian Type I strain." (PMID 32194558, 2020). "Conversely, macrophages isolated from ccl3−/− mice were more susceptible to infection by the Colombian strain trypomastigotes." (PMID 32194558, 2020). "Instead, infection with candidalysin-deficient strains resulted in decreased CCL3 levels, the ligand for CCR1, and decreased renal pelvis damage and neutrophil-mediated immunopathology." (PMID 31401652, 2019). "In our study, expression of mRNA encoding Ccl3 in the vagina was also increased at 28 days post-infection." (PMID 26779389, 2015). "We therefore conclude that MIP-1α/CCL3 chemokine is produced during inflammation, caused by eggs during S haematobium infection, in which infection is associated with increased MIP-1α/CCL3 levels in an egg intensity-dependent manner." (PMID 19852800, 2009). "However, infection reduced the expression of several chemokines upregulated by 4T1, including monocyte recruitment factors Csf1, Ccl3, Ccl6, Ccl9, Ccl24 and EMT-associated Cxcl1." (PMID 40547518, 2025). "LdCen-/- parasite induced increased expression of CCL3 in neutrophils caused higher recruitment of DCs capable of inducing a strong proinflammatory response and elevated co-stimulatory molecule expression compared to LdWT infection." (PMID 35192633, 2022). "Our first multiple regression model confirmed the results from the univariable immunological analysis and showed a positive association of CCL17 and CCL3 higher responders and a high frequency of IL-17 responders with S. mansoni active infection in the study population." (PMID 33777015, 2021). "Inflammatory monocytes recruited by chemokine CCL3 produced in the intestinal mucosa by ICLs cells in dependence upon IL-18 in the intestine are associated with the ability to suppress early parasite replication at the site of infection." (PMID 33324583, 2020). "The reason for the higher procoagulant activity with RacL11 is unknown, but similar results have been reported for chemokine gene expression patterns, with RacL11 causing higher levels of CCL2 and CCL3 mRNA in equine PBMC than NY03 or Ab4 after 24 h of infection." (PMID 23497076, 2013). "Unlike growth factors like recombinant PDGF-BB (Becaplermin), which showed limited efficacy and raised safety concerns, CCL3 appears to combine efficacy in infection control and wound repair with a good systemic tolerability profile." (PMID 41597195, 2026). "CCL3 production also appeared to be greater after infection, but the difference from that in uninfected cells was significant only at 24 hpi." (PMID 41280933, 2025). "Meanwhile, the expressions of Slc11a1, Havcr2, Ccl12, Sirt1, Ifng, Ccl3, and Trem2 were higher during the whole infection process." (PMID 40170749, 2025).
infection (continued). "Elevated chemokines like C-C Motif Chemokine Ligand 2 (CCL2) and C-C Motif Chemokine Ligand 3 (CCL3) suggested increased recruitment of more immune cells to the infection site." (PMID 39928675, 2025). "Our findings revealed a significant upregulation in the Ccl3 and Ccl4 mRNA expression in isolated and differentiated M1 macrophages 24 h after BA.5 infection." (PMID 40452816, 2025). "When investigating differences between the infection routes, we found an enrichment of CCL3+ T cells and MHCII+ macrophages following intravenous infection." (PMID 40178612, 2025). "Nonetheless, local inflammatory responses in the lung, i.e. leukocyte infiltration and CCL3 overexpression, reflect a successful infection and an effective administration of BFA even in a more limited immune reaction." (PMID 40178612, 2025). "Analysis of macrophage‐related cytokines and chemokines found that Tnf, Il1b, Il1a, Ilrn, Il17ra, Cxcl1, Cxcl2, Ccrl2, Ccl3, Ccl4, and Ccl9 expression significantly increased over the course of infection." (PMID 41117166, 2025). "In neonatal Swiss mice, USUV infection led to an increase in typical neuroinflammatory cytokines, including IL-6, CCL3, CCL4, CCL5, CXCL9, and CXCL10, with CXCL10 being upregulated to the highest level in this model." (PMID 39907280, 2025). "In contrast, the presence of macrophage inflammatory protein-1α (MIP-1α/CCL3) in bovine serum was rather unexpected since this chemokine is produced by leukocytes during an inflammatory response to infection." (PMID 40076881, 2025). "IL‐37 mitigates the infiltration of macrophages and suppresses the production of macrophage‐associated chemokines (such as CCL3 and CCL4) induced by SARS‐CoV‐2 Omicron infection through NF‐κB signaling pathway." (PMID 40452816, 2025). "IL-1β, IL-12 (p40), IL-4, and CCL3 levels were modulated, showing significantly lower induction during early infection (1–9 h) followed by a significant increased after 12 h." (PMID 38538626, 2024). "In contrast, IL-1α was decreased at day 4 after infection, whereas IL-5, CCL3, CCL4 (MIP-1β), and IFN-γ were significantly reduced in IkkαLyve-1 BALF at day 7 after infection." (PMID 39007717, 2024). "For example, CCL3, which is highly upregulated during infection with C. violaceum, can bind to CCR1 (along with several other chemokines), and CCL3 can also bind to CCR5 (again, along with several other chemokines)." (PMID 38352492, 2024). "Nectin-1 was redistributed, at the protein level, in adjacent uninfected cells surrounding infection, inducible by CCL3, IL-8 (or CXCL8), and possibly CXCL10 and IL-6, thus facilitating spread." (PMID 38857290, 2024). "While pDCs attract CD4 T cells to the site of infection via their pro-inflammatory chemokines (CCL3-5), they also inhibit HIV entry as these chemokines bind to CCR5 and with their IFN production, they inhibit viral spread." (PMID 38924030, 2024). "The chemokine CCL3 is one among the several chemokines which are released by NK lymphocytes during immune response to infection." (PMID 39407208, 2024). "The mice that received cidal (cipro) treated cEC1 had statistically significantly higher serum levels of TNF, IL12p40, and CCL3 at 1 h post infection than the mice that received static (tet) treated cEC1." (PMID 39609397, 2024). "Intriguingly, similar to the M1-type microglia and macrophages, the DCs respond to inflammation and infection by secreting inflammatory cytokines like IL-6 and IL-12 and chemokines CCL3, CCL4, CXCL8, and CXCL10 to recruit immune cells." (PMID 36902456, 2023). "IL-1β, IL-12 (p40), IL-4, and CCL3 levels were modulated, showing significantly lower induction during early infection (1–9 hrs) followed by a significant increased after 12hrs." (PMID 37790429, 2023).
infection (continued). "Several DEGs specific to cytokines Cxcl1, Cxcl2, Ccl3, and Il1b were upregulated in bone-marrow-derived macrophages at both 1 and 24 h post-infection with Bb validating the mRNA abundance observed in scRNA-Seq analysis of infected splenocytes." (PMID 38149246, 2023). "Typical inflammatory chemokines, including Ccl4, Ccl3, Cxcl2, Cxcl3, and Cxcr2, induces immune cells to enter the site of infection during the immune response." (PMID 37580334, 2023). "In AGM, the expression of Ccl2, Ccl3, Ccl4, Ccl7, and Ccl8 together with Cxcl10 and Cxcl11 also increases during infection, although more rapidly and with a more marked expression in nonpolarized rAM than in hamsters." (PMID 37350967, 2023). "CCL3 plays a crucial role in the recruitment and activation of macrophages, especially at sites of infection or inflammation." (PMID 37511404, 2023). "Both CCL2 and CCL3 play roles in monocyte chemotaxis to sites of inflammation and are known to be markers of severe infection with Mycobacterium tuberculosis." (PMID 36912627, 2023). "Infection with LdWT or LdCen-/- parasites led to a significant induction of CCL3 secretion from infected neutrophils compared to uninfected neutrophils." (PMID 35192633, 2022). "Infection of neutrophils with either LdWT or LdCen-/- parasites resulted in an increase in CCL3 mRNA level by an average of 3-fold and 7-fold over uninfected neutrophils respectively." (PMID 35192633, 2022). "Consistent with our in vitro results, we also observed that neutrophils responding to LdCen−/− parasites in ear dLN augmented CCL3 expression, which played a critical role in attracting DCs 5d post infection." (PMID 35192633, 2022). "Infection with A. actinomycetemcomitans as a single species caused a significant increase in IL-2, CXCL1, CCL-3/MIP1α, and G-CSF levels compared to sterile implants." (PMID 35203495, 2022). "Infection led to robust induction of chemokine and interleukin genes, including Il1b, Il6, Ccl2, Ccl3, Ccl4, Ccl7, Cxcl1, Cxcl2, Cxcl5, Cxcl9, and Cxcl10, and related receptor genes, including Ccr1, Ccr4, Ccr5, Ccr5, Ccr7, Cxcr2, Cxcr5, Il1r2, and Il1rn." (PMID 35487885, 2022). "Next, we evaluated CCL3 protein levels in culture supernatants of uninfected and infected neutrophils 24h after infection." (PMID 35192633, 2022). "Next, we studied how neutrophil derived CCL3 influences DC recruitment in vivo to ear dLNs of C57BL/6 mice following ID injection with PBS or LdWTor LdCen-/- parasites 5d post infection." (PMID 35192633, 2022). "The impact of neutrophil depletion on the ability of CCL3 treatment to boost infection control in diabetic wound was assessed by MPO analysis (i) and CFU count determination (h & j) in day 1 wounds." (PMID 35112667, 2022). "After STM infection migratory ILCs express significantly higher levels of Ccl3, Gbp2, Gbp6, Irf1, Irf4, Irf7, Pml and Stat1, all of which are regulated in response to interferon gamma." (PMID 33414524, 2021). "In response to H1N1 or H3N2, there was a marked elevation of Ccl3, Ccl4, Ccl5, and Cxcl10 in young lung at day 3 post infection." (PMID 34829979, 2021). "In tissues treated prior to infection, baseline production of IL-1β, IL-22, CCL3, CCL4 and CCL5 varied between BaL- and LAI-infected explants, possibly reflecting virus difference in cell tropism and subsequent CD4 T cell depletion." (PMID 34835109, 2021). "Next, we defined proinflammatory macrophages as cells expressing high levels of CCL2 and CCL3, chemokines involved in recruitment of adaptive and innate cells to sites of infection, and which were also characterized by the expression IL6, IL1B, and TNF." (PMID 33622974, 2021). "Both CCL2 and CCL3 mRNA levels were elevated by almost 1000-fold on days 5 and 6 after infection consistent with the high level of virus in the brain." (PMID 33477869, 2021).